TGFB1 (transforming growth factor beta 1)
Diseases named in the same sentence as TGFB1 in open-access papers (continued):
Sharing a sentence is not in itself a finding about the gene and the disease.
Insulin resistance (125 papers, 2010 to 2026). Increased resistance towards insulin, that is, diminished effectiveness of insulin in reducing blood glucose levels. "This study shows that increased circulating levels of TGFβ1 under diabetic conditions are associated with the increased activation of TGFβ1, insulin resistance, and accelerated progression of kidney fibrosis and renal dysfunction." (PMID 36430743, 2022). "One of the mechanisms by which TGFβ1 and associated signalling has been proposed to contribute to the development of insulin resistance is by ECM remodelling." (PMID 34707569, 2021). "We found clear evidence that signals for IL-1β, IL1RN, TNF-α and TGFβ-1 are present in both adipose and liver tissues and that these are linked to the development of inflammation and insulin resistance in the HFC-fed mice." (PMID 21410952, 2011). "In addition, associations between TGFβ1 and insulin resistance and the development, differentiation and function of pancreatic islet β-cells have also been found." (PMID 37626717, 2023). "In addition, insulin resistance has been associated with increased Serpine1 and Tgfb1 expression in the heart contributing to the development of cardiac fibrosis." (PMID 34948369, 2021). "Conversely, compared with a high-lard diet, a high-fish oil diet resulted in a lower degree of systemic inflammation and insulin resistance that were associated with a lower adipocyte diameter as well as lower immunoreactivity for transforming growth factor β 1 (TGFβ1) in white adipose tissue." (PMID 24562331, 2014). "Another important observation that supports the role of TGFβ1 overexpression in insulin resistance in the present study is the significant difference in the glucose levels between the diabetic TGFβ1 TG mice and diabetic WT mice." (PMID 36430743, 2022). "In particular, the activation of SMAD3 appears to play a critical role in TGFβ1-mediated insulin resistance." (PMID 36430743, 2022). "For example, TGFβ1 and its intracellular SMAD signaling pathway have been associated with insulin resistance in women with polycystic ovary syndrome." (PMID 36430743, 2022). "In the present study, we used HepG2 cells and L6 myotubes to evaluate whether TGFβ1 induces insulin resistance in vitro." (PMID 36430743, 2022). "The remodeling of the extracellular matrix by TGFβ1 in the skeletal muscles may also contribute to insulin resistance." (PMID 36430743, 2022). "In this study, we aimed to determine whether TGFβ1 is in part responsible for the development of insulin resistance and/or aberrant insulin signalling, previously observed in the skeletal muscle and myotubes of women with PCOS." (PMID 34707569, 2021). "Based upon its role in the pathophysiology of PCOS and preliminary evidence, we attempted to establish if TGFβ1 is a circulating factor that could contribute to the development of skeletal muscle insulin resistance." (PMID 34707569, 2021). "To examine whether TGFβ1 could contribute indirectly to insulin resistance by the accumulation of the ECM, we assessed pro-fibrotic factor CTGF and collagen1α1; 1α2 and 3α1 which account for a large percentage of the ECM." (PMID 34707569, 2021). "In addition, TGFβ1 may also contribute to insulin resistance through its modulatory activity on SMAD-independent pathways, including mitogen-activated protein kinases and Akt." (PMID 36430743, 2022). "Insulin resistance and increased expression of angiotensin/AT1 and TGFβ1 were major changes related to inflammasome activation, increased NFκB, activation of stellate cells and increased fibrosis." (PMID 27853271, 2016). "Collectively, our findings show that short-term treatment with TGFβ1 does not appear to influence insulin signalling or promote insulin resistance in myotubes." (PMID 34707569, 2021). "However, the calculated values of the homeostasis model assessment for insulin resistance (HOMA-IR) were significantly increased in the diabetic TGFβ1 TG mice compared to the diabetic WT mice and non-diabetic TGFβ1 TG mice." (PMID 36430743, 2022).
Insulin resistance (continued). "In conclusion, TGFβ1 treatment in myotubes increased glucose uptake, suggesting that short term increased serum TGFβ1 or localised TGFβ signalling dysfunction are unlikely to induce insulin resistance via defects in insulin signalling in the skeletal muscle." (PMID 34707569, 2021).
aneurysm (123 papers, 2009 to 2025). Bulging or ballooning in an area of an artery secondary to arterial wall weakening. "TGFB1 gene expression in the PBMCs of intracranial aneurysm (IA) patients was significantly higher than in healthy individuals, suggesting that TGFB1 may contribute to the molecular mechanisms underlying aneurysm formation." (PMID 40563991, 2025). "In our study, the expression of TGFB1 in PBMC was lower in AAA patients compared to controls, which presumably may reflect decreased TGF-beta 1 signaling in aortic tissue, previously associated with the development of aneurysm." (PMID 37569462, 2023). "In summary, our study highlights that TGFB1 expressed by PBMCs primarily contributes to aneurysm formation, while TGFB3 is associated with aneurysm rupture." (PMID 40563991, 2025). "TGFB1 expression was diagnostically useful in identifying individuals with aneurysms, with an AUC of 0.671." (PMID 40563991, 2025). "Compared to patients with aneurysm and healthy controls, the highest levels of TGFβ1 were detected in the MMD group (6,666 ± 1,181 vs. 2,684 ± 399, 2,651 ± 530, p < 0.05)." (PMID 35873760, 2022). "The plasma TGFβ1 levels were higher in the patients with ischemic MMD than in the aneurysm and healthy patients (p < 0.05)." (PMID 35873760, 2022). "The risk for development of aortic dissection and aneurysms is increased in patients with genetic diseases resulting in a defective TGFB-signaling, where PCSK6 is one of the key proteases involved in the TGFB1 axis." (PMID 32325687, 2020). "This mutation is associated with accelerated activation of transforming growth factor β (TGFβ1) which contributes to the formation of aneurysms in the root of the aorta." (PMID 29483877, 2018). "We not only show that such targeted delivery regresses aneurysms, but we also show that such therapy restores elastin lamina, decreases matrix metalloproteinase (MMPs), immunomodulating cytokine TGFβ1, and infiltration of activated macrophages at the aneurysmal site." (PMID 32218565, 2020). "Others have shown that TGFβ1 administration exacerbates aneurysms." (PMID 32218565, 2020). "TGFβ1 neutralization either worsened or mitigated aneurysm formation, depending on whether treatment was initiated before or after the establishment of the aneurysm in a thoracic aorta." (PMID 32218565, 2020). "Since TGFβ1 and fibronectin are known to be regulated in aneurysms and ASncmtRNA-2 is expressed in aortas, it might be interesting to test if ASncmtRNA-2 plays a role in aneurysm formation." (PMID 30893946, 2019). "Evaluating gene expression in PBMCs provides novel insights into the involvement of inflammatory cells and TGFB1 and TGFB3 in aneurysm formation and rupture." (PMID 40563991, 2025). "A recent review further highlighted that both activation and inhibition of TGFβ1 disrupt its vital role in maintaining normal vascular biology, potentially leading to aneurysm formation by triggering both canonical and noncanonical signaling pathways." (PMID 39742002, 2024). "Additionally, we plotted the ROC curve for TGFB1 expression, demonstrating its utility in identifying aneurysms (AUC = 0.671), whereas TGFB3 expression was significantly effective in identifying ruptured aneurysms (AUC = 0.792)." (PMID 40563991, 2025).
endometrial cancer (122 papers, 1998 to 2025). Primary or metastatic malignant neoplasm involving the endometrium (mucous membrane that lines the endometrial cavity). "On the other hand, the microarray gene-expression profiling of the high-risk recurrence endometrial carcinomas undoubtedly revealed a prominent role of TGFβ1 signaling in acquiring an aggressive phenotype." (PMID 34501347, 2021). "Together with further studies, unresponsiveness to TGFβ1 isoform in the case of endometrial cancer suggests that escape from the inhibiting impact of TGFβ signaling occurs at the early stages of carcinogenesis." (PMID 34501347, 2021). "In our research, also, it can be determined that, together with an increase in the histopathological differentiation of endometrial cancer, the expression of TGFβ1 is increasingly lowered (G3 > G2 > G1 > C)." (PMID 33917330, 2021). "The metastatic potential of tumor cells can be reversed by SB-431542, a specific TGFβ1 inhibitor, which in effect precludes further persistent endometrial carcinoma invasion." (PMID 34501347, 2021). "The present study investigates the inhibitory effects of SOE on the motility and invasion of endometrial cancer cells under the stimulation by TGFβ1." (PMID 27527140, 2016). "The overexpression of TGFβ1 in endometrial cancer cells correlates with tumor metastasis and a poor patient outcome." (PMID 27527140, 2016). "Clinical studies have shown that a significant increase in levels of TGFβ1 in the serum of patients with breast cancer, lung cancer, hepatoma, prostate cancer, and stage I and stage II endometrial carcinoma." (PMID 27527140, 2016). "Therefore, unlike in other cancers, CHD4 acts as a tumor suppressor gene in endometrial cancer via modulation of the TGFB1/CD133 pathway." (PMID 40004553, 2025). "Observed positive correlation between mRNA levels of TGFβ1 and TGFβ1-induced expression of FXYD5/dysadherin is associated with pronounced invasive phenotype of endometrial cancer, depicted by myometrial invasion > 50%, grade 3, and intermediate/high risk of recurrence." (PMID 34501347, 2021). "The TGFβ1 seems to mediate communication between endometrial carcinoma and stromal cells, and its deregulated expression may confer with endometrial carcinogenesis." (PMID 34501347, 2021). "Therefore, we can not exclude the possibility that the impairment of SRC activity can contribute directly, or has a synergistic effect with the decrease of CD44 co-receptor level, to dampen the EGF-induced or TGFβ1-induced mesenchymal marker expression in the NMU-knockdown endometrial cancer cells." (PMID 26849234, 2016). "A recent report suggested that knockdown of CHD4 or its mutations (R975H or R1162W) is implemented with increased expressions of TGFB1 and CD133 (cancer stem cell marker), followed by the progression of uterine (endometrial) cancer." (PMID 40004553, 2025). "Elevated expressions of TGFB1 and CD133 were reported in the activation of endometrial cancer cells." (PMID 40004553, 2025). "In the final stage, the expression changes of TGFβ1, NOTCH1, and BCL2L on the protein level were assessed within G1–G3 endometrial cancer specimens in comparison to the control." (PMID 33917330, 2021). "The main cytokines secreted by CAFs isolated from human endometrial cancer tissue include MCP-1, CCL5, RANTES, interleukin-6, and -8 (IL-6, IL-8) VEGF, EGF, HGF, FGF-2, as well as TGFβ1 isoform." (PMID 34501347, 2021). "As confirmed using two endometrial cancer cell lines—HEC 1A and RL95 2—the acquisition of metastatic phenotype is observed upon the stimulation with TGFβ1 isoform." (PMID 34501347, 2021). "This study reveals that SOE can inhibit TGFβ1-induced cell wound healing, cell migration, and cell invasion in a dose-dependent manner in RL95-2 and HEC-1A endometrial cancer cells." (PMID 27527140, 2016).
endometrial cancer (continued). "The inclusion criteria of literature selected for this review included the search in PubMed of the National Library of Medicine using the following keywords: “TGFβ1-3” or “TGFβR1” or “TGFβR2” or “Smad1-7” or “betaglycan/TGFβR3” or “endoglin/CD105” and “human endometrium” or “endometrial cancer”." (PMID 34501347, 2021). "As demonstrated, molecules secreted by CAFs, i.e., TGFβ1, EGF, HGF, and FGF-2, potentiate the migration and invasion of endometrial cancer cells (RL-952) when administered exogenously, thus inducing lung metastasis in vivo in mouse subcutaneous xenograft assay." (PMID 34501347, 2021). "When compared, endometrial cancer displays higher mRNA expression of TGFβ1 than adjacent non-cancerous endometrium." (PMID 34501347, 2021). "In this study, SOE treatment effectively inhibited the migration and invasion of RL95-2 and HEC-1A endometrial cancer cells in a dose-dependent manner, with or without stimulation by TGFβ1, as determined by wound healing analysis and the Boyden chamber assay." (PMID 27527140, 2016). "Further, BPA up-regulates the expression of other TGFβ isoforms, TGFβ2 and TGFβ3 transcripts but not TGFβ1, in neural tissue and endometrial cancer cells, respectively." (PMID 24586524, 2014). "Third, HtrA1 RNA and protein expression was decreased in human endometrial cancers vs. normal controls, with significant negative correlations between HtrA1 and TGFβ1 levels, and HtrA1 protein expression and endometrial cancer grade." (PMID 22761798, 2012). "However, the observed variation in TGFβ1 protein expression is not accompanied by elevated mRNA level, which is dramatically reduced in endometrial carcinomas." (PMID 34501347, 2021).
inflammatory bowel disease (119 papers, 2011 to 2026). A spectrum of small and large bowel inflammatory diseases of unknown etiology. "Typical manifestations of TGFB1 deficient patients include inflammatory bowel disease (IBD) and recurrent infections which can be lethal are reported as well." (PMID 34512655, 2021). "Several cytokines are essential to maintain tolerance to the gut microbiota, as evidenced by the association of IL-10, FoxP3 or TGFβ1 function in mice or humans with inflammatory bowel disease (IBD) or autoinflammatory disorders." (PMID 22624013, 2012). "A prior study of inflammatory bowel disease demonstrated the ability of TGFβ1 signaling inhibition to suppress CLDN4 expression." (PMID 35281827, 2022). "Interestingly, a wide variety of cytokines such as IL-13, IL-10, and TGFβ1 have been demonstrated to participate in the innate and adaptive immune response to inflammatory bowel disease (IBD)." (PMID 36776842, 2023). "In this context, it is interesting to note that IEC isolated from patients with the inflammatory bowel disease, Crohn’s disease, have a highly reduced ability to induce Treg-cell-promoting DC, as well as reduced Aldh1a2 and Tgfb1 expression as compared to healthy controls." (PMID 34084164, 2021).
endothelial dysfunction (113 papers, 2009 to 2026). In vascular diseases, endothelial dysfunction is a systemic pathological state of the endothelium (the inner lining of blood vessels) and can be broadly defined as an imbalance between vasodilating and vasoconstricting substances produced by (or acting on) the endothelium. "This is further augmented by low levels of TGFβ-1 adding to endothelial dysfunction and inhibition of wound healing." (PMID 34249765, 2021). "In response to SARS-CoV-2 infection, TGFB1 may be upregulated, leading to excessive inflammation and endothelial dysfunction." (PMID 37239234, 2023). "Endoglin (also known as CD105) is a membrane co-receptor for transforming growth factor-β, which is released into the circulation in a soluble form and disrupts TGFβ1 signaling in the endothelium, thereby promoting inflammation, endothelial dysfunction, cardiac fibrosis, and vascular remodeling." (PMID 34957261, 2021). "Lung remodeling is thought to occur following repetitive injuries leading to alveolar epithelial cells (AEC) apoptosis, proliferation of fibroblasts and Transforming growth factor beta 1 (TGFβ1)-induced myofibroblast differentiation as well as endothelial dysfunction." (PMID 34829703, 2021).
lung disease (109 papers, 2004 to 2026). "Previous work demonstrated that TGFbr2F/F;Nkx2.1-cre mice are protected from lung disease caused by transgenic overexpression of TGFβ1 or neonatal hyperoxia treatment." (PMID 38187712, 2024). "This consortium grew from the need to increase sample size and carry out replication studies and demonstrated its utility in a report that showed variants in the TGFB1 gene associate with pulmonary disease (discussed in more detail below)." (PMID 23630497, 2013). "The association of TGFβ1 codon 10 CC genotype and the TT genotype of −509 with more severe lung disease in delta F 508 homozygous cystic fibrosis patients was shown by Drumm and coworkers in a large trial involving 808 CFTR F508 del homozygous patients." (PMID 24062613, 2013). "As alluded to above, the first significant association identified by the consortium approach demonstrated that severity of pulmonary disease tracked with variants in the TGFB1 gene." (PMID 23630497, 2013). "So our protocol was only able to assess the ανβ8-dependent part of TGFβ1 contributing to lung disease." (PMID 24062613, 2013). "In fact, the activation of TGFβ1 by αvβ6 has been proposed as a potential therapeutic target for fibrotic lung diseases." (PMID 23547562, 2013). "In contrast to the findings of Arkwright, they showed a significant association of the TGFβ1 +869CC and not +869TT genotype with more severe lung disease." (PMID 24062613, 2013).
rheumatoid arthritis (109 papers, 2009 to 2026). A chronic, systemic autoimmune disorder characterized by inflammation in the synovial membranes and articular surfaces. "The results of studies from the United Kingdom have shown that TGFB1 rs1800470 is associated with ischemic heart disease in patients with rheumatoid arthritis." (PMID 36672663, 2023). "We aimed to investigate the expression of pro-inflammatory cytokine genes TNFA, IL6, IL12B, IL23, IL18 and immunoregulatory genes FOXP3, TGFB1, and IL10 in the peripheral blood of patients with rheumatoid arthritis (RA) at messenger ribonucleic acid (mRNA) level." (PMID 38534783, 2024).
squamous cell carcinoma (109 papers, 2002 to 2025). A carcinoma arising from squamous epithelial cells. "In the paper entitled “The role of TGFβ signaling in squamous cell cancer: lessons from mouse models,” A. Glick summarizes the current literature on the role of TGFβ1 in normal tissues and in carcinogenesis." (PMID 23819053, 2013). "DDR-deficient types had lower expressions of STING1 (p = 0.01), CD28 (p = 0.020), HLA-DRB6 (p = 0.014) in adenocarcinoma, lower TNFRSF4 (p = 0.017), and TGFB1 expressions (p = 0.033) in squamous carcinoma, and higher CD40 (p = 0.012) and TNFRSF14 expressions (p = 0.022) in SCLC." (PMID 34604048, 2021). "TGFβ1 expression is significantly higher in A549 lung tumor, but not in A431 epidermoid carcinoma." (PMID 32974124, 2020). "In the present study, the levels of α-smooth muscle actin (α-SMA), TGFβ1 and HGF were determined immunohistochemically in oesophageal precancerous lesions (low- and high-grade intraepithelial neoplasia; LGIEN and HGIEN, respectively), carcinoma in situ (CIS) and squamous cell carcinoma (SCC)." (PMID 24137336, 2013).
Arthritis (106 papers, 2006 to 2026). Inflammation of a joint. "Baseline IL-17 and CXCL10 expression was especially prominent in cases of ICI-induced arthritis, whereas TGFβ1 was linked to both ICI-induced arthritis and colitis." (PMID 30400835, 2018). "Interestingly, upstream regulator analysis identified TNF (p = 2.34 × 10-36), TGFB1(p = 9.02 × 10-36) and IL-1B (p = 2.39 × 10-32) as known senescence and arthritis associated regulators of DEG miRNAs." (PMID 36213127, 2022). "In addition, joint levels of TGFβ1, IL-10, IFNγ, IL-4 and IL-17 mRNAs were augmented in WT mice with arthritis." (PMID 22438945, 2012). "In this study, we first confirmed the therapeutic effects of MSCs on CIA mice, using generally applied quantification methods, including the paw thickness, clinical arthritis score, histological arthritis score, and modulation of proinflammatory cytokines, like IL-1β, IL-6, TNF-α, IL-10 and TGFβ1." (PMID 27354158, 2016).